INS (insulin)
Diseases named in the same sentence as INS in open-access papers (continued):
Sharing a sentence is not in itself a finding about the gene and the disease.
Stroke (continued). "The nomogram incorporates seven common clinical characteristics: age, marital status, CHF, CHD, stroke, creatinine levels, and taking insulin." (PMID 40060382, 2025). "In the present study, GLP-1 RA therapy was associated with a significantly reduced risk of hospitalization for stroke compared to both DPP-4 inhibitors and sulfonylureas in patients with T2D on insulin." (PMID 41011236, 2025). "The study identified seven predictors, including age, marital status, congestive heart failure (CHF), coronary heart disease (CHD), stroke, creatinine level, and taking insulin." (PMID 40060382, 2025). "Previous stroke, DM requiring insulin therapy, and neurosurgeries have been validated as strong risk factors for PIS." (PMID 39838692, 2025). "Our findings suggest that abdominal adiposity is related to post-stroke functional outcomes through a pathway distinct from that of insulin." (PMID 38206990, 2024). "The chart highlights the disparity in post-prandial insulin levels among the two groups, suggesting a possible correlation between postprandial insulin levels and the incidence of stroke." (PMID 39347227, 2024). "We also found that diabetic retinopathy, diabetic foot ulcer, nontraumatic lower-extremity amputation, ischaemic heart disease, stroke, insulin, antiplatelet agents, and higher numbers of antihypertensive agents were associated with DKD." (PMID 38528132, 2024). "Prompt treatment with insulin for blood glucose level (BGL) >10 mmol/l post-Stroke Guideline inclusion was significantly lower (pre-guideline: 34 %, post- guideline: 30 %; p = 0.041)." (PMID 39507681, 2024). "As for nephrotoxic substances, patients at our stroke center are kept on IV fluids and nil per os in the first 24 h, with minimal drug exposure during this period consisting of IV fluids, insulin, and drugs for blood pressure and temperature control." (PMID 39597868, 2024). "This cohort study is a post hoc analysis of the Prevention Regimen For Effectively Avoiding Second Strokes (PRoFESS) and Insulin Resistance Intervention After Stroke (IRIS) secondary prevention clinical trial datasets." (PMID 39028666, 2024). "GSK-3 is a negative regulator of insulin signaling, and Gsk-3 was found to be activated immediately after the initiation of the oxidative stress pathway in stroke." (PMID 39655056, 2024). "Previous studies, including the UK Glucose Insulin in Stroke Trial, have demonstrated that insulin infusions lead to a significant decrease in plasma glucose levels compared to the saline group." (PMID 38295137, 2024). "They included ECG traits, demographics, serum electrolytes, sugars, lipids, and clinical and disease traits (T2D, HbA1C, TC, QRS, SBP, QTc, smoking, glucose, RR, potassium, LDL-C, PW, TG, BMI, DBP, insulin, stroke, HDL-C, and PR)." (PMID 38202283, 2024). "Among insulin users, stroke was the most prevalent cardiovascular complication (28 events), followed by heart failure (23 events)." (PMID 39295783, 2024). "The variables most strongly related to stroke occurrence were age, fasting insulin, and postprandial insulin levels." (PMID 39347227, 2024). "The European Stroke Organization guidelines recommend insulin treatment only if the blood glucose level exceeds 180 mg/dL." (PMID 39335345, 2024). "The inflammatory state in patients with stroke and cardiovascular disease reduces insulin sensitivity." (PMID 36997874, 2023). "The study showed a 4.33-fold increase in stroke among candidates with lower insulin sensitivity (measured by the PREDIM index) and muscle weakness versus those with higher levels of both parameters." (PMID 38034217, 2023). "Second, insulin resistance affects platelet adhesion, activation, and aggregation, leading to stroke through arterial stenosis or occlusion." (PMID 37296457, 2023). "WALTER N KERNAN was the most prolific author, whose research mainly focused on insulin resistance intervention after stroke (IRIS) trial." (PMID 36950100, 2023).
Stroke (continued). "In T2DM, in acute conditions, such as acute MI, stroke, or congestive heart failure, insulin is the main indicated treatment; otherwise, the recommended therapeutic approach includes antidiabetic non-insulin drugs." (PMID 37298707, 2023). "The relationship of IR with stroke was further supported by a Japanese prospective cohort study that showed that reduced insulin sensitivity and muscle strength independently increased the risk of SLI in elderly patients." (PMID 38034217, 2023). "Indeed, the impairment of the IRS1/2/PI3K/Akt pathway (triggering insulin signaling) leads to the loss of pro-angiogenic, anti-oxidative and anti-inflammatory actions in genetically obese Zucker rats and studies as such should also be performed in the brain after stroke." (PMID 36835405, 2023). "To further demonstrate the specific role of decreased insulin sensitivity in stroke recovery in a preclinical setting of clinical relevance, we utilized middle-aged mice that spontaneously developed early IR." (PMID 36835405, 2023). "Intensive glucose control with intravenous insulin effectively reduces in-hospital mortality in critically ill non-stroke patients." (PMID 37025208, 2023). "AF incidence was higher in the subgroups of age > 65 years, CKD, prior MI or stroke, insulin use, DM duration > 5 years, and use of anti-hypertensive medication." (PMID 36658574, 2023). "Although the mechanisms of how adipose tissue specific insulin resistance affects the prognosis of stroke are unclear, there are several possible explanations." (PMID 38041145, 2023). "Lymphocyte count, insulin treatment, heart failure, stroke, liver condition, and renal failure showed significant differences in DR (P < 0.05)." (PMID 36187629, 2022). "Dietary fiber exerted a beneficial effect on stroke probably by improving blood lipid profile, glucose, insulin sensitivity, chronic inflammation and fibrinolytic activity." (PMID 36337616, 2022). "We confirmed that elevated levels of serum cortisol were associated with a higher prevalence of stroke and cardiovascular risk factors (deceased ß cell function, HDL-C, and fasting insulin as well as increased TG, LDL-C, FPG, and HbA1c)." (PMID 35761983, 2022). "Over the study period, ARNI did not significantly lower the HbA1c level compared to ACEIs or ARB after adjusting confounding factors (age, stroke, insulin use, calcium channel blocker use, estimated glomerular filtration rate)." (PMID 35690600, 2022). "The fasting insulin and fasting glucose were measured on 14 ± 3 days after stroke or before discharge." (PMID 35260102, 2022). "In the study of glycemic index of stroke patients, acupuncture significantly improved glycosylated hemoglobin and insulin sensitivity index compared with western medicine." (PMID 36107536, 2022). "A meta-analysis on glucagon-like peptide-1 (GLP-1) receptor agonists like liraglutide, which work by glucose-dependent insulin release, have shown benefits for primary stroke prevention." (PMID 35102177, 2022). "The final model included 9 characteristics (prior stroke, age, chronic kidney disease, prior MI, sex, heart failure, insulin use, atrial fibrillation, and microvascular complications)." (PMID 36030198, 2022). "The risk of stroke associated with NAFLD and CKD was more prominent in females, younger subjects, alcohol drinkers, and insulin users." (PMID 35740267, 2022). "Meanwhile, another study has proposed that strict glycemic control using insulin improved the National Institutes of Health Stroke Scale (NIHSS) after 30 days." (PMID 36079047, 2022). "DPP-4 inhibitors (0.84; 0.82–0.86), metformin (0.90; 0.89–0.91), insulin (0.92; 0.91–0.93) and sulfonylureas (0.98; 0.96–0.99) also showed moderately reduced HR for stroke/TIA." (PMID 35933524, 2022). "Patients were more likely to discontinue insulin if they were being seen by an endocrinologist, had a female provider prescribing insulin, were on a basal-bolus insulin regimen or had a stroke." (PMID 33402226, 2021).
Stroke (continued). "Compared with the TBR < 1% group, the TBR ≥ 1% group had significantly higher rate of insulin treatment and history of stroke or transient ischemic attack (TIA), and lower FPG, HbA1c, and CPI levels." (PMID 33794984, 2021). "The primary MACE outcome (cardiovascular death, myocardial infarction, or stroke) was examined according to insulin treatment and assigned study treatment." (PMID 34158057, 2021). "Two months of dietary change also improved pre-stroke insulin sensitivity versus T2D/Ob mice, but similarly to glycemia, the full normalization back to the values of the non-T2D control mice was only achieved after 4 months of dietary change." (PMID 34937562, 2021). "Stroke-induced catecholamine surge promotes the endoplasmic reticulum stress and impairs hepatic insulin signaling." (PMID 34393970, 2021). "In this retrospective cohort study, compared to basal insulin, T2DM patients with high CVD risk who were treated with liraglutide demonstrated a lower risk of a composite CVD outcome, stroke, and all-cause mortality." (PMID 33446845, 2021). "In conclusion, AG490 improved the inflammation and oxidative stress of neuronal, hepatic, and muscle tissues of stroke rats as well as impairing insulin signaling in the liver and skeletal muscles." (PMID 34943061, 2021). "Our results suggest there is a disconnect between insulin resistance at the muscle (reduced insulin activation of GS) and whole-body insulin resistance in stroke survivors." (PMID 33375333, 2020). "We demonstrate, for the first time, a direct relationship between VO2peak and M in stroke survivors suggesting that even in disabled individuals, fitness is an important indicator of insulin sensitivity." (PMID 33375333, 2020). "trial was great and showed benefit but didn’t prove to me that insulin infusions were the way to go for stroke patients." (PMID 33148343, 2020). "Stroke survivors show reduced insulin action on skeletal muscle GS independent and fractional activity compared to nonstroke individuals." (PMID 33375333, 2020). "Patients with a history of stroke and those using insulin or glucagon-like peptide-1 agonist for more than 3 months were excluded." (PMID 32563247, 2020). "Among the 379 stroke patients, 178 (46.97%) used antihypertensive drugs, 130 (34.30%) used lipid-lowering drugs, 141 (37.20%) used aspirin, and 98 (25.86%) used insulin." (PMID 32982965, 2020). "Several results have provided indications of the efficiency of low-glycemic index diets in weight management and insulin sensitivity, but also cognitive function, epilepsy treatment, stroke, and neurodegenerative diseases." (PMID 33003562, 2020). "For example, an observational study of a large US claims database found that insulin-treated T2D patients had hospitalization rates per 10 000 patient years of 97 and 151 for MI and stroke, respectively, compared with 243 for heart failure." (PMID 32485734, 2020). "Major events were also similar between the non-insulin dependent and insulin-dependent DM patients: stroke (0% vs. 0%, p = 1.000), recurrent MI (0% vs. 1.8%, p = 0.415) and MACE (p = 0.615)." (PMID 32534591, 2020). "Further adjustment for other baseline covariates (sex, BMI, prior insulin use, total serum cholesterol, previous stroke and previous TIA) had only small added effects." (PMID 31815634, 2019). "The proportion of patients with stroke, coronary artery disease, and congestive heart failure, as well as the prescription rates of sulfonylurea and insulin, were significantly higher in the HD cohort than in the PD cohort." (PMID 30934740, 2019). "A single-arm trial evaluated the efficacy of a computerized variable rate insulin infusion rate protocol in previously insulin-naïve stroke patients on continuous EN over five days." (PMID 31261760, 2019). "One individual (9.1) had a stroke at the age of 2 years while on combined insulin and thiamine therapy." (PMID 29450569, 2018).
Stroke (continued). "As these findings show potential for fitness training to contribute to secondary stroke prevention—a recognized research priority —future studies should include measures of serum lipids, insulin sensitivity, or glucose tolerance." (PMID 29920979, 2018). "The comorbidity in both the patients receiving insulin detemir and the patients receiving insulin glargine were similar except for the number of patients with a diagnosis of stroke." (PMID 28970434, 2017). "Before stroke, the CR animals were characterized by a reduction in body weight, adipose tissue mass, circulating insulin, IGF1, and free fatty acids (FFA) levels as compared to the ad libitum‐fed animals." (PMID 28961383, 2017). "By day 14 after stroke, insulin levels significantly increased in aged CR rats as compared to the young (1.7‐fold) and AL aged (2.8‐fold) animals." (PMID 28961383, 2017). "We also did correlation analyes among RPC-reactive IgG levels, complement activation products levels and other clinical characteristics in the DR patients such as weight, body mass index, insulin usage, renal problems and stroke." (PMID 26839120, 2016). "Body mass index, previous history of stroke, use of statins were higher in low variability group; insulin use was higher in the high variability group." (PMID 26747793, 2016). "In the INSULINFARCT trial, we randomly divided 180 patients with < 6 hours carotid territory stroke into groups receiving intensive insulin therapy or standard subcutaneous insulin treatment." (PMID 25793765, 2015). "The rate of stroke was nearly threefold higher in the insulin compared to the other treatment groups." (PMID 25616979, 2015). "Diabetic ketoacidosis (DKA) is a condition, arising due to infection, inadequate insulin or poor insulin compliance, acute pancreatitis, stroke, drugs, metabolic disturbances within the body, or negligence with the treatment." (PMID 26273667, 2015). "Rates of HF, MI, and stroke were higher among patients in insulin group compared to those in the EBID or EBID + insulin groups." (PMID 25616979, 2015). "Among patients taking SU (n = 19282, 49%), the observed adjusted risk reductions for HF, MI, stroke and MI or stroke in the EBID and EBID + insulin groups were similar to those observed in the overall analysis." (PMID 25616979, 2015). "We observed that patients with HbA1c above 58.5 mmol/mol (7.5%) in the EBID and EBID + insulin groups had significantly lower risks of HF and MI or stroke than analogous patients in the insulin group." (PMID 25616979, 2015). "And if stroke is related to the overall insulin demand of the diet, it is expected to be more strongly related to dietary GL than to dietary for GI, as we have observed." (PMID 23717392, 2013). "It is therefore necessary to use models where insulin resistance and insulin levels can be experimentally manipulated prior to stroke." (PMID 23344061, 2013). "It has been shown to be involved in insulin secretion from pancreatic beta cells and is a strong candidate as a biomarker for endocrine tumors, stroke, and eventually psychiatric conditions." (PMID 22888312, 2012). "We analyzed the effects of insulin therapy, age and gender on the risk of ischemic heart disease (IHD) and cerebrovascular accident (CVA) according to glycemic control." (PMID 21978180, 2011). "Female participants, individuals using insulin and those with a history of stroke showed a trend toward being less likely to rate their health as positive (0.05 < P-value < 0.10)." (PMID 20500890, 2010). "Further, indirect support that milk fat per se may affect stroke risk factors is gained from a cross-sectional study where high fat dairy consumption was inversely related to risk factors, for example blood pressures, insulin, waist and triacylglycerol, while low-fat dairy consumption was not." (PMID 19457271, 2009).
Stroke (continued). "The published epidemiological data from the DIGAMI-2 trial reported a significant increase in the cumulative endpoint of death, reinfarction and stroke (hazard ratio of 1.42) for those administering insulin subsequent to an MI event." (PMID 19804622, 2009). "The age, life-course socioeconomic position, smoking, and physical activity adjusted hazard ratio for a combined outcome of incident coronary heart disease or stroke per one standard deviation of fasting insulin was 1.14 (95% CI 1.02–1.33)." (PMID 17760500, 2007). "T2D duration >12 years; insulin treatment; cardiovascular diseases (e.g., CAD, stroke, peripheral artery disease, heart failure); weight loss >5 kg in 6 months; inability to exercise; participants currently being treated with more than three glucose-lowering medications." (PMID 40034634, 2025). "Early identification of at-risk individuals could facilitate the implementation of targeted interventions to improve insulin sensitivity and reduce the burden of stroke." (PMID 40134698, 2025). "Insulin‐treated diabetic patients have a higher risk of stroke compared to those treated with oral medication or nondiabetic patients." (PMID 41383356, 2025). "Our previous study further indicated that DPP-4 inhibitor use in insulin-treated patients with T2D was linked to a lower stroke risk compared with non-DPP-4 inhibitor use." (PMID 41011236, 2025). "Higher BMI is positively associated with an increased risk of new-onest stroke, while lower eGDR, indicative of reduced insulin sensitivity, demonstrates a negative association with stroke risk." (PMID 40417114, 2025). "Meanwhile, our study also suggests that improving insulin sensitivity and regulating CRP and uric acid levels may be important for preventing the risk of stroke occurrence." (PMID 39634177, 2024). "Newly diagnosed T2D patients who received early insulin therapy, compared with those who did not receive such treatment, had 31% lower risk of incident stroke, and 28% lower risk of hospitalization for HF." (PMID 38844816, 2024). "Cardiorespiratory exercise can improve cardiac function, hypertension, insulin sensitivity and fitness following stroke and may also improve post-stroke cognition." (PMID 38762542, 2024). "The sensitivity analysis showed that daily average tea intake remaining inversely associated with total CVD, stroke, and CHD risk, even in individuals with centrally obese participants, or further adjustment for the use of insulin, TC and TG, the substitution of waist circumference for the BMI." (PMID 38308353, 2024). "It has also been demonstrated in animal experiments that lowering glucose by insulin further reduces brain injury after stroke, suggesting that stress hyperglycemia may be a potentially modifiable risk factor." (PMID 38216864, 2024). "Notably, pathways involved in oxidative stress and insulin signaling have similar effects in Drosophila and mammals, suggesting further exploration of these pathways in models of stroke are warranted." (PMID 38584778, 2024). "Given these mixed findings, our study aimed to examine the risk of stroke by analyzing the association between the presence of stroke and multiple metabolic variables, with a particular focus on the significant role of insulin levels (both fasting and postprandial) in stroke occurrence." (PMID 39347227, 2024). "Improving insulin sensitivity and regulating CRP and uric acid levels may be important for preventing the risk of stroke occurrence." (PMID 39634177, 2024). "SGLT2 inhibitor users had a lower prevalence of chronic kidney disease, heart failure, and a history of stroke, and they were more likely to have used insulin, metformin, and glucagon-like peptide-1 (GLP1) agonists in the baseline period when compared to DPP4 inhibitor users." (PMID 38846094, 2024). "The use of insulin increased from 27.7% pre-stroke to 37.5% during follow-up." (PMID 38812009, 2024).